CST1 (cystatin SN)
Diseases named in the same sentence as CST1 in open-access papers (continued):
Sharing a sentence is not in itself a finding about the gene and the disease.
asthma (16 papers, 2016 to 2026). "Several studies of airway epithelial, bronchial and nasal tissue showed repeatedly that CST1 is linked to asthma development outlining it as a potential biomarker and a candidate therapeutic target in allergic patients." (PMID 38270326, 2024). "Our results indicate that the overexpression of CCL26 as well as CST1 causes a downregulation of several antiviral response genes which has previously been seen in patients with asthma and allergy." (PMID 38270326, 2024). "ROC curves also displayed that CST1 in nasal and bronchial epithelium both manifested excellent diagnostic efficiency for Th2-high asthma." (PMID 36733482, 2023). "The ROC curves indicated that CST1 in the bronchial epithelium exhibited excellent diagnostic efficiency for Th2-high asthma in GSE41861 dataset." (PMID 36733482, 2023). "Analysis of the GSE41861 dataset showed that upregulation of CST1 in nasal mucosa was associated with asthma." (PMID 36059464, 2022). "In this study, we found that asthma participates in the pathogenic mechanism of ACRSwNP by upregulating the expression level of CST1 in the upper airway, and CST1 is associated with the expression level of the type 2 inflammatory cytokine receptor IL5RA." (PMID 36059464, 2022). "A recent study explored the relationship between COPD and blood eosinophil count and airway epithelial transcriptome, showing that CST1 was the only gene positively associated with blood eosinophil count in asthma and COPD patients." (PMID 36059464, 2022). "The transcriptome thus showed little overlap between genes associated with linear blood eosinophil counts in asthma versus COPD with CST1 the only gene associated with eosinophilic asthma and COPD meeting FDR control." (PMID 31506971, 2020). "In addition, it is worth noting that the CST1 expression level in the nasal epithelium also showed an ideal diagnostic efficiency for Th2-high asthma." (PMID 36733482, 2023). "According to the ROC curve, CST1 showed excellent diagnostic efficiency for Th2-high asthma." (PMID 36733482, 2023). "Finally, we validated the expression level of CST1 in Th2-high asthma group, Th2-low asthma group, and healthy control group, and the diagnostic efficiency of CST1 in distinguishing Th2-high asthma from Th2-low asthma by using the GSE67472 dataset." (PMID 36733482, 2023). "In addition, asthma developed from AR may have higher levels of CST1 expression and be more prone to Th2-high asthma, which is associated with high airway reversibility and more significant reductions in lung function compared to non-Th2 asthma." (PMID 36733482, 2023). "Upregulation of CST1 in bronchial or nasal epithelium of asthmatic patients, highlights the role of CST1 in the pathophysiology of asthma." (PMID 38270326, 2024). "Venn Diagram tool analysis showed that CST1 was the only key gene that was up-regulated in both nasal epithelium and bronchial epithelium of AR and asthma patients." (PMID 36733482, 2023). "In the lower airways, CST1 was highly expressed in AR comorbid asthma patients compared with AR alone." (PMID 36733482, 2023). "CST1 was the only key gene that was upregulated in both the upper and lower airways in patients with asthma and AR, and its expression levels in the upper and lower airways had a high correlation." (PMID 36733482, 2023). "We performed differential analysis on the expression levels of CST1 in the nasal epithelium and bronchial epithelium among AR comorbid asthma, AR, and healthy subjects in GSE101720 dataset." (PMID 36733482, 2023). "Compared with normal controls, the expression level of CST1 was up-regulated in both nasal and bronchial epithelium of AR comorbid asthma and AR alone." (PMID 36733482, 2023). "In this study, by applying WGCNA to analyze transcriptomic data from the upper and lower airways, we found that CST1 and its related molecular functions played a key role in AR comorbid asthma and were potential biomarkers of airway allergic diseases." (PMID 36733482, 2023).
asthma (continued). "Validation of datasets showed that CST1 was the only gene that was up-regulated in both upper and lower airways in patients with AR and asthma, and correlation heatmaps showed that CST1 was the gene with the highest sum of correlation coefficients." (PMID 36733482, 2023). "Targeted treatment of CST1 has the potential to prevent the development of asthma in AR patients and deserves further study." (PMID 36733482, 2023). "This study showed that CST1 and its related molecular functions played a key role in AR comorbid with asthma." (PMID 36733482, 2023). "CST1 expression was further upregulated in ECRSwNP patients with asthma comorbidity and the expression level was correlated with the percentage of eosinophils in tissue samples." (PMID 36059464, 2022). "Combined with the analysis results of GSE41861, we found that CST1 is highly expressed not only in the inflamed nasal mucosa and nasal polyps in ACRSwNP, but also in the nasal mucosa and bronchial epithelium of asthma patients." (PMID 36059464, 2022). "CST1 is highly expressed in the airway epithelium of Th2-high asthma patients, and is one of the biomarkers to distinguish Th2-high from Th2-low asthma." (PMID 36059464, 2022). "The overlap was minimal between the genes and pathways associated with the blood eosinophil count identified in asthma and COPD with CST1 the only gene meeting FDR criteria." (PMID 31506971, 2020). "The gene expression profiles between the high and low eosinophil groups of COPD and asthma were broadly different with the exception of one gene CST1 that was the gene most positively related to a blood eosinophil count in both diseases." (PMID 31506971, 2020). "CST1 was weakly correlated to the blood eosinophil count in our replication asthma and COPD cohorts." (PMID 31506971, 2020). "Additional research should be conducted on targeted therapy for CST1, as it may help AR patients avoid developing asthma." (PMID 39964644, 2025). "CST1 has been considered as a potential biomarker for monitoring asthma control." (PMID 38891935, 2024). "In a recent study, sputum and serum CST1 protein levels were negatively correlated with lung function in asthma patients; CST1 protein levels were significantly lower in the serum of HDM-specific IgE-positive asthmatic patients than in that of sIgE-negative asthmatic patients." (PMID 38891935, 2024). "Moreover, the HDM-induced epithelial barrier function disruption was suppressed by recombinant human CST1 protein in vitro and in vivo, reducing asthma symptoms." (PMID 38891935, 2024). "However, a previous study found a significant increase in the number of intraepithelial mast cells in Th2-high asthmatics compared with Th2-low asthmatics, and our results showed CST1 was highly expressed in Th2-high asthma." (PMID 36733482, 2023). "CST1, POSTN, CPA3, and SERPINB2 were key genes that potentially linked AR and asthma." (PMID 36733482, 2023). "CST1 plays a key role in the development of AR comorbid asthma and may be a biomarker for airway allergic diseases." (PMID 36733482, 2023). "Furthermore, a search of the GSE41861 expression matrix revealed that CST1 was also upregulated in the bronchial epithelium of asthma patients compared to normal controls." (PMID 36059464, 2022). "We found key asthma-associated genes including the T2-high signature genes of CLCA1, POSTN, and SERPINB2 as well as those not previously asthma-associated (e.g., CST1 and Vanin genes—VNN1–3) to be potentially influenced by aberrant H3K27ac." (PMID 33362848, 2020). "Epithelial eQTL could detect more specific biomarkers for different phenotype of asthma, such as CDHR3 associated with asthma in children with severe exacerbation, and CST1, which can differentiate asthmatic with EIB from those with no EIB." (PMID 27658857, 2016).
asthma (continued). "Based on our result that CST1 was significantly positively correlated with activated CD4 memory T cells, it can be inferred that blocking the expression of CST1 in the airway may prevent the development of asthma by inhibiting the activation of CD4 memory T cells." (PMID 36733482, 2023). "The upregulation of CST1 in the entire airway (including nasal mucosal epithelium and bronchial epithelium) lead by AR may act as a primary driver with an initiating factor in the development of asthma in AR patients." (PMID 36733482, 2023). "In addition, CST1 is also upregulated and acted as a potent upstream initiator of epithelial-derived type 2 inflammation in chronic rhinosinusitis with nasal polyps, another nasal disease that is closely related to asthma." (PMID 36733482, 2023). "Furthermore, our findings found that asthma may be involved in the pathogenesis of ACRSwNP by altering the expression levels of upper airway genes, of which CST1 is one of the key genes." (PMID 36059464, 2022). "We further used a one-to-one format for comparison and validated with the GSE63142 dataset The genes CEACAM5, PRR4, CPA3, POSTN, TCN1, CST1 (Cystatin-SN), CLCA1, TPSAB1 and NOS2 (Nitric oxide synthase 2) were highly expressed in patients with asthma." (PMID 39963184, 2025). "PRR4, TCN1, CST1, CLCA1, and NOS2 were also highly expressed in patients with asthma in GSE158752 dataset." (PMID 39963184, 2025). "Our results highlight the role of CST1 and CCL26 in asthma development due to their role in inflammation." (PMID 38270326, 2024). "In conclusion, our study identified CST1 as a potential biomarker for airway allergic diseases by applying WGCNA, analyzing the upper and lower airway transcriptomic data of AR and asthma." (PMID 36733482, 2023). "Venn diagram analysis results demonstrated that CST1, POSTN, CPA3, and SERPINB2 were not only candidate genes in key modules but also DEGs in AR and asthma." (PMID 36733482, 2023). "In both asthma and COPD, CST1 was the gene most positively related to a blood eosinophil count and indeed was the only gene that met FDR criteria in both asthma and COPD." (PMID 31506971, 2020). "CST1, CLC, FETUB and VSMT1 were upregulated in asthma and allergic diseases in nasal studies, which could reflect overrepresentation of allergic diseases in our non-TB control group." (PMID 41542684, 2026). "Obtaining more knowledge about the mechanistic insights of those genes, it might be possible to identify whether CST1 and CCL26 can be potential drug targets for asthma treatment." (PMID 38270326, 2024). "Increased expression of CST1 and CCL26 has been previously shown in nasal epithelium of children with asthma and allergy, however, the functional mechanism of how it contributes to asthma development is so far not well understood." (PMID 38270326, 2024). "Even though several studies showed an association between increased levels of CST1 and CCL26 and the development of asthma, it was to our knowledge so far not possible to understand the contribution of CST1 and CCL26 in the disease development." (PMID 38270326, 2024). "Therefore, the aim was to investigate the functional mechanisms of CST1 and CCL26 in an alveolar basal epithelial cell line to understand their function in asthma pathogenesis better." (PMID 38270326, 2024). "In addition, the volcano plot showed that CST1, POSTN, CPA3, and SERPINB2 were significantly up-regulated in the bronchial epithelium of asthma and nasal epithelium of AR." (PMID 36733482, 2023). "The expression of CST1 in the nasal epithelium in asthma does not appear to be additive with that in AR, suggesting that the inflammatory disease of the upper and lower airways is a whole." (PMID 36733482, 2023). "In addition, by retrieving the expression of CST1 in the dataset GSE104468, it was verified that CST1 was upregulated in the nasal mucosa and bronchial epithelium of asthma patients." (PMID 36059464, 2022).
asthma (continued). "Analysis of CST1 expression levels in different comorbidities revealed that in the nasal epithelium of AR, CST1 expression levels were not significantly altered, regardless of whether asthma was accompanied or not and whether asthma was controlled or not." (PMID 36733482, 2023). "Moreover, the expression level of CST1 was significantly positively correlated with the expression levels of POSTN, CPA3, and SERPINB2 in the bronchial epithelium of AR patients and in the nasal epithelium of asthma patients." (PMID 36733482, 2023). "Therefore, CST1 and CCL26 might be considered as potential drug targets for asthma treatment." (PMID 38270326, 2024). "Unfortunately, due to the lack of data on CST1 expression in the lower airways of patients with asthma alone on the same platform, we could not know whether the expression level of CST1 is higher in patients with asthma comorbid AR than patients with asthma alone." (PMID 36733482, 2023).
colon cancer (10 papers, 2013 to 2025). "In agreement with our data, higher CST1 expression was significantly associated with worse survival of colon cancer patients in TCGA bulk RNA-Seq data." (PMID 34921160, 2021). "Interestingly, examination of the cDNA sequence of CST1 showed that the CGC codon encoding Arg-91 (R) was mutated to CGA (silent mutation R91R) in colon cancer tissues." (PMID 24357805, 2013). "The CST1 upregulation in colon cancer patients and CRC cell lines was confirmed by RT-PCR, immunohistochemistry, and western blot analyses." (PMID 39949372, 2025). "In this study, we revealed that CST1 mRNA and protein expression are elevated in colon cancer tissues and cell lines compared to levels in normal tissues." (PMID 28300829, 2017). "We next investigated CST1 mRNA and protein levels in the colon cancer cell lines COLO205, DLD-1, HCT-116, HT-29, LoVo, RKO, and SW480." (PMID 28300829, 2017). "To examine the relationship between CST1 expression and AF-induced cell death in colon cancer, we performed cell viability assays on the colon cancer cell lines following treatment with various doses of AF." (PMID 28300829, 2017). "To examine CST1 mRNA levels in colorectal cancer tissues, we performed for real-time PCR and found that CST1 mRNA expression was approximately 8-fold higher in colon cancer tissues than in normal tissues." (PMID 28300829, 2017). "CST1-overexpressing colon cancer cell lines exhibited increased tumor growth as well as metastasis in a xenograft nude mouse model." (PMID 26569312, 2015). "To examine the underlying mechanism(s) by which CST1 increases tumor growth, we monitored the primary growth of CST1- and CST3-overexpressing colon cancer cells using a xenograft assay." (PMID 24357805, 2013). "We next determined the role of CST1 upregulation in colon cancer and the function of the interaction between CST1 and CST3 in the extracellular space." (PMID 24357805, 2013). "We performed WB detection of CST1 and GPX4 proteins in 5 matched colon cancer tissues and adjacent normal intestinal mucosal tissue samples." (PMID 36369321, 2023). "In order to explore whether the expressions of CST1 and GPX4 are also related in other tumor tissues, we selected colon cancer tissues and cells for experiments." (PMID 36369321, 2023). "In this study, we showed that CST1 was highly expressed in colon tumor tissues, compared with nontumor regions." (PMID 24357805, 2013).
colorectal cancer (10 papers, 2013 to 2025). A primary or metastatic malignant neoplasm that affects the colon or rectum. "High CST1 expression was also reported by previous studies to be linked to poor survival in colorectal cancer, pancreatic cancer, and non-small cell lung cancer patients, which was consistent with our results." (PMID 28523467, 2017). "Additionally, serum cystatin SN (CST1) was also reported to be a valuable diagnostic biomarker for colorectal cancer and ESCC." (PMID 38077439, 2023). "CST1, a cysteine protease inhibitor, is overexpressed in GC and has been shown to promote tumor cell proliferation, migration, invasion, and activate Wnt/β-catenin signaling; it is also implicated in colorectal cancer proliferation via modulation of the Wnt pathway and as a let-7 target." (PMID 40725485, 2025). "Overexpression of CST1 also contributed colorectal cancer growth via reducing intracellular reactive oxygen species (ROS) production." (PMID 33968941, 2021). "Our previous study showed that high CST1 expression enhances tumor metastasis and invasiveness in colorectal cancer." (PMID 28300829, 2017). "For example, the salivary cystatins CST1, CST2, CST3, and CST4 were associated with both local invasion at the early stage and remote metastasis in colorectal cancer." (PMID 28523467, 2017). "They observed that Cystatin SN mRNA and protein were specifically up-regulated in colorectal cancer cell lines (3-fold) and tissues, respectively." (PMID 25648368, 2015). "At the same time, CST1 was also identified as a tumor marker for colorectal cancer although this finding lacks the support of clinicalpathological data." (PMID 23711283, 2013). "Cystatins (CST1) play important roles in tumor invasion and metastasis in colorectal cancer." (PMID 31692905, 2019). "Furthermore, Cystatin SN protein was elevated in the serum and urine of patients with colorectal cancer compared with healthy controls (1.70 ng/ml vs. 1.12 ng/ml)." (PMID 25648368, 2015). "The mechanisms here elucidated indicate that CST1 may inhibit AF-induced CRC death in vitro by triggering ROS production, suggesting that CST1 may represent a potential target for colorectal cancer therapy." (PMID 28300829, 2017).
esophageal squamous cell carcinoma (8 papers, 2017 to 2025). Esophageal squamous cell carcinoma (ESCC) is a type of esophageal carcinoma (EC) that can affect any part of the esophagus, but is usually located in the upper or middle third. "The Kaplan-Meier method was utilized to examine the association between serum CST1 levels and prognosis in a cohort of 118 preoperative patients diagnosed with esophageal squamous cell carcinoma (ESCC)." (PMID 38414741, 2024). "Serum CST1 has the potential to function as a diagnostic indicator for distinguishing early-stage esophageal squamous cell carcinoma (ESCC) from individuals with benign esophageal lesions and healthy individuals." (PMID 38414741, 2024). "CST1 was identified as one of the top 1-25 differentially expressed genes (DEGs) associated with esophageal squamous cell carcinoma (ESCC) based on data obtained from the TCGA database." (PMID 38414741, 2024). "A tumor-specific CST1+ myofibroblast subset with prognostic value and potential biological significance exists in esophageal squamous cell carcinoma." (PMID 37853464, 2023). "Subsequently, the patients with esophageal squamous cell carcinoma (ESCC) were categorized into two groups: high serum CST1 group and low serum CST1 group." (PMID 38414741, 2024). "However, the roles of CST1 and miR-942-5p on esophageal squamous cell carcinoma (ESCC) are still unknown up to now." (PMID 36848349, 2023). "Contradictorily, CST1 shows higher expression in peritumoral tissues than in the esophageal squamous cell carcinoma (ESCC) tissues." (PMID 29383149, 2017). "The study revealed a significant elevation in serum CST1 levels among patients with early-stage esophageal squamous cell carcinoma (ESCC) (7.41 ± 4.32 ng/ml) compared to those with esophageal benign lesions (4.67 ± 2.43 ng/ml) (p < 0.0001) and healthy controls (4.87 ± 2.77 ng/ml) (p < 0.0001)." (PMID 38414741, 2024). "However, the relationship and roles of CST1 and OXPHOS in esophageal squamous cell carcinoma (ESCC) remains unclear." (PMID 38424293, 2024).